ENSG00000252459
Synonyms: LOC124900329
Gene: Small nucleolar RNA gene on chromosome 12 (114,737,704 to 114,737,798, forward strand). Ensembl gene ENSG00000252459.
Gene Ontology:
Biological process: RNA processing
Cellular component: nucleolus
Homologues: Paralogues in human: SNORA27 (78% identical).